SMAD3 (SMAD family member 3)
Diseases named in the same sentence as SMAD3 in open-access papers (continued):
Sharing a sentence is not in itself a finding about the gene and the disease.
cancer (continued). "Cancer cell‐derived sEVs transferred TGF‐β1, leading to a wound‐healing response in myofibroblasts by eliciting Smad3 signaling cascade." (PMID 33508878, 2021). "As a result of increased TGF-β activity, the levels of phosphorylated (active, when phosphorylated at S423/S425) Smad3, which is a TGF-β transcription factor, were significantly upregulated in the studied cancer cells/tissues." (PMID 33295886, 2020). "The administration of TGF-β1 increased the migration and invasion of EVI5-knockout NSCLC cells, and increased the levels of p-Smad3 and its downstream signaling molecules, indicating a therapeutic role for EVI5 in inhibition of cancer metastasis." (PMID 32393392, 2020). "Via Smad2/Smad3 and transforming growth factor β (TGF-β) signaling, increased FOXP1 expression restrained CD8+ T cells from proliferation and activation in cancer." (PMID 32719717, 2020). "SMAD3, a member of the SMAD family, is reported to play an essential role in TGF-β1-mediated cancer progression." (PMID 32774166, 2020). "In this study, we discovered that TGF-β1/Smad3 signaling increased IRX4 expression and NANOG-mediated cancer cell stemness." (PMID 32820157, 2020). "pERK will phosphorylate SMAD3 through SMAD1 that eventually translocate SMAD4 to the nucleus and activate collagen production genes in cancer cells." (PMID 33294017, 2020). "TGF-β, secreted by cancer cells and stromal fibroblasts in the cancer microenvironment, is considered as a primary inducer of EMT through inducing SNAIL expression and cooperating with Smad2 and Smad3 and WNT/β-catenin signaling." (PMID 31126310, 2019). "As a member of the SMAD family, SMAD2 plays a key role, together with SMAD3 and SMAD4, in TGF-β signaling and cancer progression." (PMID 31762811, 2019). "The TGF-β signaling pathway is involved in cell sensitization to pro-apoptotic events in colonocytes, and downregulation of mothers against decapentaplegic homolog 3 (SMAD3), a TGF-β regulatory gene, leads to cancer progression." (PMID 30862015, 2019). "Confocal microscopy also demonstrated that few p-Smad3(+) and p-JNK(+) cells were seen in normal human kidney from the uninvolved pole of carcinoma nephrectomy samples." (PMID 31447676, 2019). "More importantly, the expression of SMAD3 and its different phosphoisoforms may have location heterogeneity in primary tumors; however, serum exosomes, as a liquid biopsy substrate, reflect the comprehensive expression of SMAD3 in all cancer cells of primary tumors." (PMID 29991801, 2018). "miRNA-491 has been evaluated mostly in cancer, but it has been shown that target mRNAs involved in strong profibrotic pathways including TGF-β/SMAD3/NF-κB and Wnt3a/β-catenin signaling pathways." (PMID 30530916, 2018). "QRT-PCR was utilized to investigate SMAD3 and PAX6 expression levels in 20 normal and 20 NSCLC cancer tissues." (PMID 30594196, 2018). "Western blotting analysis indicated that the levels of phosphorylated of Smad2 protein (p-SMAD2), p-SMAD3 and p-SMAD4were significantly elevated in CAF-CM and TGF-β1-treated cancer cells, suggesting that CAFs activated the TGF-β1/SMAD signaling pathway." (PMID 29325547, 2018). "Of all the predicted targets of microRNA-145, Smad3 is integral in view of its role in versatile TGF-β diverse signaling networks in both homeostasis and disease pathogenesis such as cancer." (PMID 29156696, 2017). "Previous studies have proven that SMAD3 is a downstream signal transduction molecule of TGF-β signaling pathway, it is a antioncogene and down-expression in some malignant tumors." (PMID 29029409, 2017). "Our results established a previously unappreciated mechanism by which the miR-1/Smad3-HIF-1α axis suppressed the Warburg effect and cancer progression." (PMID 28471448, 2017).
cancer (continued). "Knockdown of KLF17 expression in multiple cancer cell lines showed similar decrease in Smad3 mRNA levels, substantiating that KLF17 induces Smad3 expression in multiple cells." (PMID 25766320, 2015). "Among the highly correlated cancer samples, two displayed low levels of KLF17 and Smad3 expression (KLF17− and Smad3−)." (PMID 25766320, 2015). "Our mechanistic study provides an insight to the well-known observation that both KLF17 and TGF-β/Smad3 can regulate ID1 and impinge on cancer cell metastasis." (PMID 25766320, 2015). "NUR77 is frequently elevated in cancers and NRIP1 promotes mitogenic signalling in the developing mammary gland, while SMAD3 and STAT3 are known to be fundamental mediators of growth factor and cytokine signalling." (PMID 25261374, 2014). "To examine the prognostic roles of ALDH2, CCNE1 and SMAD3, we tested their protein expressions in FFPE samples of cancer and adjacent normal tissues from 103 patients with UTUC using IHC assay." (PMID 25408144, 2014). "Among the proteins which have role in EMT, we chose Smad3 because it is involved in TGF-β pathway and is highly expressed in several cancers." (PMID 24551812, 2013). "For instance, SMC1A, CDC20, SMAD3 and BUB1 are all example AbG-0.5 kb genes known to promote cell cycle progression and proliferation in various cancer cell types." (PMID 24086155, 2013). "Interestingly, genes associated with TGFβ pathway accounted for 10% of directly bounded genes by SMAD3, but many of the pathways affected by TGFβ1/SMAD3 identified using a combination of ChIP-on-Chip and microarray analysis were consistent with the roles of TGFβ in development, fibrosis and cancer." (PMID 21625455, 2011). "Compared to RWPE-1, cancer cells showed stronger H3K27ac signals, and MIR1204, IER2, SMAD3, and FOXA1 were SE-associated in PC-3 and DU145 but not RWPE-1." (PMID 41330917, 2025). "This relationship is supported by correlated expressions of SMAD3 and MALT1 in cancer data (TCGA)." (PMID 40338274, 2025). "The interplay between SMAD3, NOTCH signaling, and the immune microenvironment represents a conserved mechanism that may be relevant to other cancers characterized by TGF-β-driven progression and immune evasion." (PMID 40361382, 2025). "First, we found that ZEB1, SNAI1, SNAI2, TWST1, SMAD3, and HIC1, known to be affected upon EMT in both the RPE and forms of cancer, are preferential repressors in hiPSCs compared to RPE, likely acting as preventive developmental gatekeepers under physiological conditions." (PMID 40565279, 2025). "Other targets of phosphorylation of CDK4 and CDK6 may also be of therapeutic interest in cancer, including transcription factors FOXM1, SMAD3 and NFAT4." (PMID 40699853, 2025). "Overall, NAT10 drives HCC progression via SMAD3 mRNA stability regulation, and NAT10‐2023 could be a promising therapeutic candidate for targeting NAT10 in cancer treatment." (PMID 41476650, 2025). "Additionally, we found increased TGFB1 and SMAD3 RNA levels, key components in the TGF-β1/SMAD signaling known to promote EMT and metastasis in cancer." (PMID 39398277, 2024). "Other non-significant cancer-associated genes with significant isoform switch expression include IFNAR1, SMAD3, and LAMA3." (PMID 38059347, 2024). "Additionally, LINC01405 upregulation led to the increased cell populations, proliferation, and upregulation of critical cancer‐related genes, including AKT1, AKT3, mTOR, WNT3A, SMAD3, CYCLIN D1, CYCLIN D2, BCL2, and GSK3B." (PMID 38225865, 2024). "Mechanistically, NSDHL knockdown impaired the cancer stemness characteristics of BCSCs by suppressing TGF-β signaling, which in turn decreased the secretion of TGF-β 1 and TGF-β3, inactivated Smad2 and Smad3, and downregulated the expression of SOX2 and NANOG, key regulators of cancer stemness." (PMID 39516821, 2024).
cancer (continued). "Through Smad3-dependent signalings, transforming growth factor-β (TGF-β) suppresses the development, maturation, cytokine productions and cytolytic functions of NK cells in cancer." (PMID 38878186, 2024). "Importantly, SMAD2 and SMAD3 are directly activated by TGFβ receptors, and bufalin exerted inhibitory effects on the SMAD2 and SMAD3 in cancer cells." (PMID 36903477, 2023). "Herein, we believe that the Smad3 inhibitor, SIS3, could be used to attenuate the progression of malignant tumors." (PMID 36792585, 2023). "Since accumulating studies have confirmed that TGF-β/Smad3 signaling plays extensive regulatory roles in the development and progression of multiple types of cancers, we next conducted Western blot assays to assess the effects of SCRN1 knockdown on the activity of TGF-β/Smad3 signaling." (PMID 37691034, 2023). "Importantly, EZH2-mediated SMAD3 methylation not only rendered cancer cells more vulnerable to TGFB1 and promoted cancer cell EMT and metastasis, but also showed a positive correlation with poor patient survival." (PMID 35085106, 2022). "SMAD3 is a member of the SMAD family and the TGF-β superfamily and mediates signal transduction pathways regulating cell proliferation, apoptosis, immune surveillance, and cancer metastasis." (PMID 36123344, 2022). "Accordingly, depending on the kind of cell and clinical stage of the cancer, Smad3 works both as a negative and positive regulator of carcinogenesis by controlling various transcriptional responses." (PMID 36704357, 2022). "SMAD3 gene is also upregulated in an aging NMR brain, which may slow down the growth of cancer cells and contribute to cancer resistance." (PMID 35172813, 2022). "Given that EZH2-mediated SMAD3 K53/K333 methylation is necessary for TGFB/SMAD signaling pathway activation and cancer metastasis, we investigated whether SMAD3 methylation could be therapeutically targeted." (PMID 35085106, 2022). "Moreover, SMAD3 activates EMT-TFs, such as SNAIL and SLUG, to provoke mesenchymal transition and ultimately enhance cancer cell viability and motility." (PMID 35205713, 2022). "Conversely, LINC02470 and SMAD3 were expressed at lower levels in low-grade cancer cells or nontumor cells with higher epithelial-like traits, such as higher E-cadherin and cytokeratin 18 expression but lower N-cadherin and vimentin expression." (PMID 35205713, 2022). "Moreover, ZEB2 correlates with SMAD1 in 28 cancer types, SMAD2 in 27 cancer types, SMAD3 in 22 cancer types, SMAD5 in 28 cancer types, CTBP1 in 14 cancer types, and CTBP2 in 22 cancer types." (PMID 35723302, 2022). "In addition, by qPCR and RNA-seq we identified several cancer-related genes that regulated by AS of APEX1, which included AXIN1, GCNT2, SMAD3, CTBP2, PPARD, and FBXW11." (PMID 35780128, 2022). "Therefore, PAAD was introduced as a possible cancer type following infection with (SARS-Cov-2 family), where the SMAD3, PTEN, CREB1, and CASP3 are overexpressed simultaneously." (PMID 34155232, 2021). "More studies in recent years have reported that TGF-β mediated Smad3 rather than Smad2 played a crucial role in cancer." (PMID 33757572, 2021). "TGFβ/SMAD3 signaling can significantly impact the outcome of CDK inhibitor therapy, both through canonical signaling as a cell-cycle inhibitory pathway, as well as through immunosuppressive effects in the cancer microenvironment." (PMID 34771508, 2021). "Similarly, in cancer models, PI3K/AKT signaling has been shown to antagonize TGFβ-induced apoptosis and growth arrest by interacting directly with SMAD3." (PMID 34809697, 2021).
cancer (continued). "In addition, FOXM1B/C have been demonstrated to promote cancer progression through the interaction with other proteins, such as β‐catenin, STAT3, SMAD3, HSP70, nucleophosmin (NPM), maternal embryonic leucine‐zipper kinase (MELK), and Pin1." (PMID 33314660, 2021). "Due to its important functions in suppressing cancer growth, invasion and metastasis, and in preventing the cancer death, SIS3 was described in a patent as a novel and effective anti-cancer drug by way of regulating cellular signal transduction mediated by TGF-β/Smad3 in the USA." (PMID 32245505, 2020). "Our investigations further confirmed that TGF-β induces S423/S425-phosphorylation of Smad3 in the studied cancer cells but not in healthy human cells." (PMID 33295886, 2020). "TGF-β1-activated Smad3 therefore displays differential behaviour in human cancer and embryonic vs non-malignant cells." (PMID 33295886, 2020). "To investigate whether Smad3 was indeed playing a central role in statin effects on TGF-β activity and cancer cell viability, we tested whether SMAD3 knockdown with siRNA influenced statin effects on cancer cells." (PMID 30899443, 2019). "Studies that have shown different functional roles of Smad2 and Smad3 in cancer cells never compared the expression of Smad2 and Smad3 at protein level in cancer cells versus normal cells." (PMID 31798766, 2019). "Moreover, autophagy is critical for activation of TGF-β/Smad3–dependent signaling, leading to EMT and cancer cell invasion in HCC." (PMID 31126310, 2019). "Similar SMAD3 and PAX6 mRNA and protein expression was observed in the four cell lines, including the normal BEAS-2B human lung epithelial cells and H125, HCC827 and A549 cancer cell lines." (PMID 30594196, 2018). "Previous studies have shown that SMAD3 is involved in aggressive tumor behavior in NSCLC and might act as a potential target for the treatment of the cancer." (PMID 30594196, 2018). "Furthermore, higher SMAD3 and PAX6 protein expression was observed in the cancer cell lines compared with the healthy human lung epithelial cells (P < 0.01)." (PMID 30594196, 2018). "Therefore disruption of Smad3 enhances both the E4BP4-mediated NK cell differentiation and anti-cancer effector functions in vivo and in vitro." (PMID 28262747, 2017). "In addition, deletion of Smad3 also enhanced the anticancer activities of NK cells by increasing the levels of granzyme B, interleukin (IL)-2 and IFN-γ locally within the cancer microenvironment and in the systemic circulation." (PMID 28262747, 2017). "Among them were CEBPA and CEBPB (cell cycle regulation), RELA and CREL (NF-κB pathway), TCF7L1 (Wnt/β-catenin signaling pathway), SMAD3 [transforming growth factor beta (TGF-β) signaling], FOXO1 and NFAT, all of which are involved in cancer initiation and progression." (PMID 28344555, 2017). "Altogether, these results indicate that COX-2 plays a critical role in regulating the expansion of CD24lowCD44high and ALDH+ BCSCs downstream of the TGFβ/Smad3 signaling pathway, and further highlight COX-2 as an essential mediator of cancer stemness in basal-like TNBC." (PMID 28054666, 2017). "The Smad3-mediated suppression of E4BP4 was functionally important not only in NK cell development but also in the cancer-killing activity." (PMID 28262747, 2017). "Here we find that not all MDA-MB-231 cancer cells have similar TGF-β mediated Smad3 transcription activity and display at least two distinct migratory populations." (PMID 25744371, 2015). "In addition, the rest of TFs such as PPARG, PPARA, SMAD3, MYC, and STAT1 have been proved to be related to cancer progression." (PMID 26425543, 2015). "For example, genes with Motif 1 in Molecular Mechanisms of Cancer pathway include MAPK1, BRAF, SMAD2, FZD5, FZD8, NOTCH1 and LRP1, whereas genes with Motif 2 and/or Motif3 in the same pathway include LRP5, LRP6, MDM2, CTNND1, SMAD3, SMAD4 and SMAD7." (PMID 26040697, 2015).
cancer (continued). "In contrast, DEGs with lower expression in patient relative to healthy control fibroblasts were enriched for one KEGG category ('Pathways in Cancer' as represented by the SMAD3, LAMA4, PML and DAPK1 genes), but no GO categories." (PMID 23036268, 2012). "In contrast with our observations, others have reported that oncogenic Ha-Ras (V12-Ha-Ras) dictates the response of cancer cells to TGFβ by decreasing Smad3 stability, thus suggesting a negative role of Ha-Ras in modulating R-Smad signalling." (PMID 21362163, 2011). "In cancer cell lines, studies have demonstrated that genetic or pharmacological inhibition of MYC in MCF10A basal breast cells results in increased sensitivity to TGFB-stimulated invasion and metastasis, and signaling via Smad3 and ERK/Sp1 mediate TGFB-induced EGFR upregulation." (PMID 41373732, 2025). "In addition, dietary intake of creatine or GATM-mediated synthesis of creatine activated SMAD2 and phosphorylated SMAD3 through monopolar spindle 1 (MPS1), upregulated the expression of Snail and Slug, enhanced cancer cell metastasis, and shortened the survival of mice." (PMID 38514720, 2024). "Genes positively correlated with purity showed enrichment in cancer-related pathways and processes such as epithelial-mesenchymal transition (BASP1, COL4A1, THBS2), genes involved in the TNFA signaling via NFKB (SPSB1, SMAD3), and genes upregulated by KRAS activation (CFB, MAFB)." (PMID 37041233, 2023). "However, the regulatory roles and mechanisms of Smad3 in TME are still largely unknown, especially cancer pain." (PMID 36206343, 2022). "SRPX2 also exhibited excellent antifibrosis effect via TGFβR1/SMAD3/SRPX2/AP1/SMAD7-positive feedback loop, indicating that SRPX2 might be a therapeutic target for inflammation and cancer-related inflammation for future cancer therapeutics." (PMID 35935582, 2022). "Deletion of SMAD3 methylation inhibited the interaction between SMAD3 and its localization to cellular membrane SARA, decreases its C-terminal phosphorylation, and significantly repressed cancer cell EMT, colony formation ability, and metastasis, which phenocopied SMAD3-KO cancer cells." (PMID 35085106, 2022). "However, the profound impact of the TGF-β/SMAD3 signaling pathway during cancer metastasis has not been addressed." (PMID 35982471, 2022). "The role of SMAD3 in different cancer types has not been fully explored." (PMID 34138687, 2021). "However, little research has been performed concerning the role of Smad3 acetylation in the EMT of DN, which also plays a significant role in the EMT in cancers, such as lung cancer, nasopharyngeal carcinoma, breast cancer, and other cancer cells." (PMID 34122724, 2021). "Active initiatives to further the understanding of the role that aberrant TGFβ/SMAD3 signaling plays in the sensitivity to CDK inhibitor therapy will lead to more precise implementation of this cancer treatment modality for the management of breast and other cancers in the near future." (PMID 34771508, 2021). "However, during the course of this study we realized that in mesenchymal-type cancer cells from pancreas and breast RAC1B-induced autocrine TGFβ can stimulate ECAD expression and block cell motility through a pathway that involves SMAD3 and presumably SMAD3-dependent induction of miR-200." (PMID 33260366, 2020). "We observed that SMAD3 knockdown not only significantly reduced SBE4 luciferase activity and cell numbers in U251 MG, three GIC lines, and four other cancer lines, but also completely or partially ablated the effects of simvastatin on SBE-4 luciferase activity and cell viability in these cells." (PMID 30899443, 2019).